MYO18B (myosin XVIIIB)
Diseases named in the same sentence as MYO18B in open-access papers:
MYO18B is named in the same sentence as 40 diseases in open-access papers, as found by Europe PMC text mining. Sharing a sentence is not in itself a finding about the gene and the disease. The quoted sentences say what the papers report.
lung carcinoma (8 papers, 2008 to 2023). "MYO18B has been found to be inactivated in about 50% of lung cancers by deletions, mutations, and methylation." (PMID 39086683, 2023). "The first line of evidence showing the involvement of myosin-18s in cancer came from a report that MYO18B was found to be frequently deleted, mutated, and hypermethylated in lung cancers." (PMID 33634131, 2021). "MYO18B is a tumor suppressor gene whose deletion or mutation is associated with malignant pleural mesothelioma, ovarian cancer, lung cancer, melanoma, and pancreatic cancer." (PMID 32670437, 2020). "Moreover, MYO18B has been identified as a tumor suppressor gene whose inactivation is associated with the progression of lung cancer, colorectal cancer and ovarian cancer." (PMID 30390677, 2018). "In contrast to lung cancer, where promoter hypermethylation of this gene in transformed cells was associated with gene silencing, we observed that promoter hypomethylation of MYO18B was associated with upregulation of gene expression in a set of CIMP+ T‐ALL samples." (PMID 30575306, 2019). "Restoration of MYO18B was found to suppress anchorage-independent growth in lung cancer, indicating a possible role for metastatic suppression for MYO18B in human lung cancer." (PMID 39086683, 2023). "And overexpression of MYO18B suppressed proliferation and anchorage-independent growth of lung cancer cells, suggesting myosin-18B serves as a tumor suppressor." (PMID 33634131, 2021). "The recovery of MYO18B expression in lung cancer cell line H1299 inhibited cell growth and movement through interaction with HOMER2." (PMID 32670437, 2020). "It has been reported that coexpression of HOMER2 with MYO18B enhanced the ability of MYO18B to suppress the anchorage-independent growth of a human lung cancer cell line, suggesting that HOMER2 and MYO18B cooperate in tumor suppression." (PMID 26462029, 2015). "HOMER2 interacts with the C-terminal region of MYO18B, a candidate tumor suppressor gene involved in the pathogenesis of human cancers including lung cancer." (PMID 26462029, 2015). "It was reported that the MYO18B gene is hemizygously deleted in 60% and mutated in 15% of lung cancers, and that reduced expression of MYO18B, often accompanied by promoter DNA methylation and histone deacetylation, was observed in 70% of lung cancers." (PMID 26462029, 2015). "Accumulating data show that one of these HDAC inhibitors, TSA, can cause the reactivation of a number of tumor suppressor genes such as TGF-beta receptor type II, death-associated protein kinase, CCAAT/enhancer-binding protein α and MYO18B in lung cancer." (PMID 18301774, 2008). "In lung cancer for example, the deleted gene MYO18B was reported as a tumor suppressor." (PMID 36352274, 2022).
cardiomyopathies (7 papers, 2018 to 2025). "Human MYO18B biallelic LoF variants have been associated with cardiomyopathy, and reduced growth of the left ventricle and aortic valve; in addition, the MYO18B locus was implicated in a GWAS analysis of patients with HLHS." (PMID 40030011, 2025). "In a single family with severe NM and cardiomyopathy, we detected a homozygous truncating variant in MYO18B, coding for an unconventional myosin." (PMID 38982518, 2024). "Consistent with a role in the heart, mutations of MYO18B have been associated with cardiomyopathies." (PMID 38784114, 2024). "Some studies showed that MYO18B mutation is associated with myopathy or cardiomyopathy diseases in animal model or in humans." (PMID 35484552, 2022). "Recently, MYO18B have been associated to NM with cardiomyopathy even if NM is not typically associated with these disorders." (PMID 30517146, 2018). "Importantly, in addition to cilia-associated genes, we identified recessive variants in four genes previously implicated in cardiomyopathy (MYH6, UNC45B, MYO18B, and MYBPC3) that are expressed in embryonic cardiomyocytes; RGs in these genes contributed to left-sided CHD phenotypes." (PMID 40030011, 2025).
colorectal cancer (6 papers, 2015 to 2024). A primary or metastatic malignant neoplasm that affects the colon or rectum. "Further studies have shown that MYO18B expression is reduced in various cancers, including primary ovarian and colorectal carcinoma, and restoration of MYO18B expression in pleural mesothelioma cell lines decreased tumor growth and metastatic potential." (PMID 38784114, 2024). "The MYO18B (Myosin XVIIIB) gene, a tumor suppressor gene associated with lung, ovarian, and colorectal cancer, was strongly expressed (LFC 7.5) in a set of CIMP+ cases (7/18)." (PMID 30575306, 2019). "HOMER2 which was identified as a binding partner of MYO18B, interacted with the C-terminal region of MYO18B, a candidate tumor suppressor gene involved in the pathogenesis of human cancers including colorectal cancer." (PMID 29050227, 2017).
hepatocellular carcinoma (5 papers, 2018 to 2024). A malignant tumor that arises from hepatocytes. "In hepatocellular carcinoma patients, high MYO18B mRNA expression is significantly associated with poor survival." (PMID 32704163, 2020). "Although most studies on MYO18B in cancer support its role as a tumor suppressor, one report in hepatocellular carcinoma found that high MYO18B expression was associated with worse survival of this type of cancer, and knocking down MYO18B reduced proliferation and migration." (PMID 33634131, 2021). "In contrast, high MYO18B expression was correlated with poor prognosis in hepatocellular carcinoma and knockdown of MYO18B in HepG2 cells (human hepatocellular carcinoma cell line) decreased cell proliferation and invasiveness." (PMID 38784114, 2024). "Thus our study significantly expose the transcriptional regulatory network of MYO18B, which in future will help to study the role of these signaling pathways in myopathy, cirrhosis of the liver, and the development of hepatocellular carcinoma." (PMID 32704163, 2020). "MYO18B has been proposed to contribute to the progression of hepatocellular carcinoma (HCC)." (PMID 32704163, 2020).
dyslexia (3 papers, 2015 to 2022). A learning disorder characterized by an impairment in processing written words. "Quantitative data on mathematic ability was correlated with genome data of 200 children with dyslexia and found that the rs133885 variant in the myosin-18B (MYO18B) gene is the only marker that had an association with the mathematical ability at a statistically significant level." (PMID 35911657, 2022). "This could be very well the case in the light of the large effect size reported for the MYO18B variant of 4.87% in the combined sample of individuals (N = 699) with dyslexia." (PMID 25778778, 2015). "Therefore, it is possible that the strength of the MYO18B association in the discovery sample is specific to the phenotype used, rather than to a dyslexia definition." (PMID 25778778, 2015).
nemaline myopathy (3 papers, 2019 to 2025). Nemaline myopathy (NM) encompasses a large spectrum of myopathies characterized by hypotonia, weakness and depressed or absent deep tendon reflexes, with pathologic evidence of nemaline bodies (rods) on muscle biopsy. "MYO18B variants were previously associated with autosomal recessive Klippel-Feil syndrome (MIM 616549) which is characterized by nemaline myopathy, facial dysmorphisms and hearing loss in up to 60% of patients." (PMID 33924653, 2021). "In addition, a homozygous mutation in MYO18B, encoding an unconventional myosin, has been reported as a possible cause of nemaline myopathy in an atypical case." (PMID 31228046, 2019). "Nine of the genes for nemaline myopathy encode proteins of the sarcomere, in addition, MYO18B is also a sarcomeric protein localized to the Z lines and may yet prove to be a causative gene of nemaline myopathy, although the phenotype of affected patients is different from others reported." (PMID 31228046, 2019). "Cardiac involvement is rare in patients with nemaline myopathy, but has been identified in a few patients with defects in ACTA1, MYPN or MYO18B." (PMID 31228046, 2019).
ovarian carcinoma (3 papers, 2017 to 2021). A malignant neoplasm originating from the surface ovarian epithelium. "Mutations or silenced expression of MYO18B was subsequently found in ovarian cancers, colorectal cancers, melanoma and pancreatic ductal adenocarcinoma, and neuroendocrine cancer." (PMID 33634131, 2021). "MYO18B has been reported to be hypermethylated in ovarian cancer and important for carcinogenesis." (PMID 28641578, 2017).
aneurysm (1 paper, 2009). Bulging or ballooning in an area of an artery secondary to arterial wall weakening. "Perhaps more important to the predilection of the suprarenal aorta to aneurysm formation are the downregulation of a number of genes coding for structural extracellular matrix proteins including Lama3, Myo18b and the cytoskeletal protein Tuba8." (PMID 19580648, 2009).
hearing loss (1 paper, 2021). "Heterozygous Myo18b-knockout mice had abnormal ABR findings (IMPC), further supporting the role of heterozygous MYO18B variants in the etiology of hearing loss." (PMID 33924653, 2021).
leukemia (1 paper, 2021). A malignant (clonal) hematologic disorder, involving hematopoietic stem cells and characterized by the presence of primitive or atypical myeloid or lymphoid cells in the bone marrow and the blood. "In addition to Myc and Bcl2, other tumor-promoting genes such as Eef2 and Myh10 were upregulated in leukemia cells, whereas tumor suppressors such as Ikzf1, Ikzf2, Arid1b, Arid2, Samhd1, Bach2, and Myo18b were downregulated." (PMID 34907175, 2021).
liver cancer (1 paper, 2022). An epithelial or non-epithelial malignant neoplasm that arises from the liver. "In particular, MYO18B is related to PI3K/AKT/mTOR, a liver cancer-related pathway, and showed a positive correlation with the increase in methylation as the FLI increased over time." (PMID 35723298, 2022).
medulloblastoma (1 paper, 2023). A malignant, invasive embryonal neoplasm arising from the cerebellum. "MYO18B was also found to be somatically mutated in poorly differentiated neuroendocrine carcinoma and a possible tumor suppressor in medulloblastoma." (PMID 39086683, 2023).
metabolic syndrome (1 paper, 2022). A cluster of metabolic risk factors for CARDIOVASCULAR DISEASES and TYPE 2 DIABETES MELLITUS. "In our study, we find that MYO18B is also associated with metabolic syndrome especially rs6004865 which is associated with low HDL levels." (PMID 35484552, 2022). "Although the SNPs which we find in MYO18B are all intronic or intergenic, we still need more studies to find the relationship between MYO18B and metabolic syndrome." (PMID 35484552, 2022).
Obesity (1 paper, 2020). Accumulation of substantial excess body fat.
renal cell carcinoma (1 paper, 2024). "Interestingly, high expressions of Myo18b, Ckmt2, and Eef1a2 showed unfavorable prognoses in H&N cancer, and Sln (sarcolipin) and Tceal7 are unfavorable for renal cell carcinoma." (PMID 38686626, 2024).
serous ovarian cancer (1 paper, 2023). "For example, high FZD10, MKX, FAM83A and MYO18B methylation were related with response to platinum-based chemotherapy in advanced stage high-grade serous ovarian cancer (HGSOC), and these markers might be used to predict platinum sensitivity in HGSOC patients." (PMID 37732324, 2023).
Type 2 diabetes (1 paper, 2022). "In addition, genes that are important for muscle functions such as (MAPK1), Myosin XVIIIB (MYO18B), Homeobox C6 (HOXC6), and AMP-activated protein kinase subunit (PRK AB1) were compared between individuals with or without a family history of Type 2 diabetes." (PMID 36295527, 2022).
cancer (16 papers, 2015 to 2025). A tumor composed of atypical neoplastic, often pleomorphic cells that invade other tissues. "Additionally, small eccDNA molecules, such as those originating from the tumor suppressor gene MYO18B, have been linked to cancer progression in lung and ovarian malignancies." (PMID 39202666, 2024). "Thus, MYO18B has been associated with either tumor suppression or progression and the role of MYO18B presumably varies depending on the specific cancer type and the cellular context." (PMID 38784114, 2024). "MYO18B serves as a candidate tumour suppressor gene whose activity is involved in the progression of several cancers." (PMID 37649244, 2023). "To understand the effect of C19MC miRNA expression on MYO18B mRNA expression we chose miR-520G which is known to promote drug resistance in cancer cells." (PMID 32704163, 2020). "Evidently, our results were inconsistent with the previous findings that MYO18B was a tumor suppressor gene and downregulated in cancer tissues." (PMID 30390677, 2018). "Additionally, the levels of a small eccDNA originating from myosin 18B (MYO18B) were found to be significantly elevated in cancer patient plasma samples." (PMID 40934041, 2025). "MYO18B is regarded as a potential tumor suppressor gene in various types of cancer." (PMID 40934041, 2025). "MYO18B has been identified as a novel tumor suppressor gene in several cancers." (PMID 30390677, 2018). "Previous studies identified MYO18B as a tumor suppressor gene in several cancers." (PMID 30390677, 2018). "We then focused on the small eccDNAs originated from exons and found that two small eccDNAs were significantly enriched in cancer plasma, including one originated from MEP1A and the other originated from myosin 18b (MYO18B)." (PMID 37649244, 2023). "A report indicates that MYO18B gene is expressed along with chromosome-19 micro-RNA cluster (C19MC) and cancer testis antigens in HCCs15." (PMID 32704163, 2020). "Unlike the findings in MYO18B, MYO18A was mostly associated with cancers through gene fusion events, with MYO18A frequently found to be fused with other oncogenes such as FGFR1, PDGFRB, and MLL." (PMID 33634131, 2021).
tumor (14 papers, 2008 to 2024). "Consistent with a potential role as a tumor suppressor gene, MYO18B is inactivated by deletions, mutations, or methylation in about 50% of lung carcinomas." (PMID 38784114, 2024). "In the tumor of patient #1, we detected mutations in tumor suppressor genes such as MYO18B and CTNN2 and in genes related to adhesion, invasiveness, and survival (e.g., CDH23, HMCN1, and OBSCN) in samples collected at the resistance that were not present initially." (PMID 37620318, 2023). "To validate the result from TCGA, we thus determined the expression level of MYO18B in 80 pairs of tumor tissues and adjacent liver tissues by qRT-PCR." (PMID 30390677, 2018). "Our work found that MYO18B was obviously upregulated in tumor tissues when compared with normal tissues (P < 0.05)." (PMID 30390677, 2018). "We first analyzed the expression differences of MYO18B between tumor and normal tissues using TCGA cohort." (PMID 30390677, 2018). "The result showed that MYO18B expression exhibited higher levels in tumor tissues than adjacent liver tissues (p < 0.05)." (PMID 30390677, 2018). "In particular, we determined the expression of MYO18B in HCC tumor tissues using two independent cohorts, one from TCGA and one from our clinical patients." (PMID 30390677, 2018). "In a human squamous cell lung carcinoma cell line, Lu24, a homozygous deletion on chromosome 22q12.1 suggested the presence of a tumor suppressor gene within the deletion, ultimately leading to the identification of a novel myosin gene, denoted MYO18B, which is structurally related to MYO18A." (PMID 38784114, 2024). "The initial EMC may have been driven by SNPs in MYO18B, TRIM37, and IL7R; or loss of tumor suppressor genes on chromosome 10q." (PMID 39086683, 2023). "MYO18B expression was not evaluated in our tumor samples, so the effects of the mutations found in our tumor samples should be investigated for a possible tumor suppressor role in EMC." (PMID 39086683, 2023). "MYO18B promoted tumor growth and migration via the activation of PI3K/AKT/mTOR signaling pathway." (PMID 30390677, 2018). "In addition, we found that the tumor suppressor candidate genes kruppel-like factor 4 (klf4) and myo18b were up-regulated in this cluster." (PMID 27254593, 2016). "Other candidate tumor suppressor genes gene such as SLIT1, SEZ6L and MYO18B, were deleted in EOBRCA and consequently downregulated at the gene expression level, as reported in other solid tumors." (PMID 36352274, 2022). "In the present study, we found that MYO18B expression was significantly upregulated in both HCC tumor tissues and HCC cell line, and high level of MYO18B was correlated with a poor prognosis for patients with HCC." (PMID 30390677, 2018). "There is no earlier report on potential tumor suppressor activity of MYO1C; however, another member of the myosin-I gene family, MYO18B, has been recognized as a tumor suppressor gene candidate in lung, ovarian and colorectal cancer." (PMID 27716847, 2016).
myopathies (8 papers, 2019 to 2025). "Two independent findings of MYO18B mutations linked in human myopathies further confirmed the conserved function of myosin-18B in striated muscle development." (PMID 33634131, 2021). "Furthermore, the association of MYO18B with certain myopathies highlights the potential involvement of early clones in both normal muscle function and disease." (PMID 40052144, 2025). "MYO18B is associated with the recessive Klippel–Feil syndrome (OMIM# 616549), characterized by myopathy and facial dysmorphism." (PMID 40030011, 2025). "We chose the cytokines bFGF, IFN-γ, EGF and IL-6 that are related to myopathy and or cirrhosis, and found that, bFGF is negatively correlated and the remaining three cytokines are positively correlated to MYO18B mRNA expression." (PMID 32704163, 2020).
cardiac diseases (3 papers, 2019 to 2024). "Mutations of either Myo18a or Myo18b cause cardiac developmental defects in mouse, emphasizing their crucial role in muscle development and cardiac diseases." (PMID 33634131, 2021).
MYO18B also shares sentences with these, for which no sentence is quoted: breast carcinoma (2 papers); acute monocytic leukemia (1); Airway obstruction (1); cirrhosis of the liver (1); Dyscalculia (1); hematological malignancies (1); ischemic heart disease (1); Klippel-Feil syndrome (1); malignant pleural mesothelioma (1); microcephaly (1); Micrognathia (1); neuroendocrine carcinoma (1); neuromuscular genetic disease (1); osteosarcoma (1); pleural mesothelioma (1); Primary microcephaly (1); schizophrenia (1); small cell lung carcinoma (1); T-cell acute leukemia (1).